DSE (dermatan sulfate epimerase)
Description:
Converts D-glucuronic acid to L-iduronic acid (IdoUA) residues. Plays an important role in the biosynthesis of the glycosaminoglycan/mucopolysaccharide dermatan sulfate.
Synonyms: SART-2; SART2; DSEPI; DS-Epi1; DSEP; EDSMC2
Tractability: Antibody: UniProt predicts a signal peptide or a membrane-spanning region. PROTAC: ubiquitination databases record sites on it; its protein half-life has been measured.
Gene: Protein-coding gene on chromosome 6 (116,253,604 to 116,444,861, forward strand). Ensembl gene ENSG00000111817.
Subcellular location: Endoplasmic reticulum membrane; Golgi apparatus membrane; Cytoplasmic vesicle membrane; Microsome membrane
Pathways (Reactome):
Metabolism: DS-GAG biosynthesis
Gene Ontology:
Molecular function: chondroitin-glucuronate 5-epimerase activity
Biological process: dermatan sulfate proteoglycan biosynthetic process; chondroitin sulfate proteoglycan metabolic process; dermatan sulfate proteoglycan metabolic process; heparan sulfate proteoglycan biosynthetic process
Cellular component: cytoplasmic vesicle membrane; endoplasmic reticulum; endoplasmic reticulum membrane; Golgi apparatus; Golgi membrane
Genetic constraint (gnomAD): Loss-of-function variants: 36 observed, 84.45 expected, observed/expected ratio (o/e) 0.43, 90% interval 0.33 to 0.56. The upper end of that interval is the gene's LOEUF score, 0.56, which puts it in group 2 of 6, group 1 being the genes least tolerant of losing a copy. Missense variants: 844 observed, 1,194.4 expected, observed/expected ratio (o/e) 0.71, 90% interval 0.67 to 0.75. Synonymous variants: 405 observed, 434.6 expected, observed/expected ratio (o/e) 0.93, 90% interval 0.86 to 1.01.
Gene-disease validity (ClinGen):
ClinGen rates the evidence that DSE causes each of these diseases.
Ehlers-Danlos syndrome, musculocontractural type 2 (autosomal recessive): Definitive.
Homologues: Orthologues: chimpanzee DSE (99% identical), macaque DSE (99% identical), rabbit DSE (96% identical), pig DSE (95% identical), rat Dse (94% identical), mouse Dse (94% identical), guinea pig DSE (89% identical), tropical clawed frog dse (75% identical), zebrafish dse (65% identical). Paralogues in human: DSEL (39% identical).
Diseases named in the same sentence as DSE in open-access papers:
DSE is named in the same sentence as 25 diseases in open-access papers, as found by Europe PMC text mining. Sharing a sentence is not in itself a finding about the gene and the disease. The quoted sentences say what the papers report.
Ehlers-Danlos syndrome (8 papers, 2015 to 2026). The Ehlers–Danlos syndromes (EDS) are a clinically and genetically heterogeneous group of heritable connective tissue disorders (HCTDs) characterized by joint hypermobility, skin hyperextensibility, and tissue fragility. "Musculocontractural Ehlers-Danlos syndrome, caused by biallelic loss-of-function variants for dermatan sulfate epimerase (mcEDS-DSE), is a rare connective tissue disorder." (PMID 36902515, 2023). "Research by Maccarana and Malmström involving the long-term study of DSE has greatly contributed to the elucidation of the functions of DSE as well as DS, and understanding of the pathogenic mechanisms of Ehlers-Danlos syndrome (EDS) with mutations in DSE." (PMID 36833436, 2023). "People with mutation in PLOD1 suffer from so called kyphoscoliotic Ehlers-Danlos syndrome, a disorder reminiscent of other, rare types of Ehlers-Danlos with mutations in carbonic sulfotransferase 14 or dermatan-sulfate epimerase." (PMID 33028365, 2020). "Homozygous missense mutations in DSE cause the musculocontractural type of Ehlers-Danlos syndrome (MC-EDS), a connective tissue disorder with congenital malformations and progressive fragility-related complications." (PMID 29370293, 2018). "For example, DSE affects glycan synthesis, which is necessary for several functions in mammalian tissue cells, and mutations resulting in the loss of the DSE enzyme function can result in the form of Ehlers-Danlos syndrome, a disease that weakens connective tissues." (PMID 35806237, 2022). "Musculocontractural Ehlers-Danlos syndrome (mcEDS) is a subtype of EDS caused by mutations in the gene for carbohydrate sulfotransferase 14 (CHST14) (mcEDS-CHST14) or dermatan sulfate epimerase (DSE) (mcEDS-DSE)." (PMID 36833362, 2023). "Different homozygous mutations in human CHST14 and DSE have been linked to Ehlers-Danlos syndrome (EDS), where patients display, among other symptoms, distinctive craniofacial dysmorphism." (PMID 25793894, 2015). "Pathogenic variants in human genes encoding DSE and D4ST cause the musculocontractural type of Ehlers-Danlos syndrome, characterized by tissue fragility, joint hypermobility, and skin hyperextensibility." (PMID 36833436, 2023). "Musculocontractural Ehlers-Danlos syndrome (mcEDS) is an extremely rare subtype of EDS, caused by pathogenic variants in CHST14 or DSE (dermatan sulfate epimerase, encoded by the DSE gene), leading to severe connective tissue fragility." (PMID 40760347, 2026). "DSE, dermatan-sulfate epimerase, catalyzes the reaction between chondroitin sulfate and dermatan sulfate, which is a key step upstream of glycosylation processes, and missense mutations in the DSE gene have been found to be a cause of one type of Ehlers-Danlos syndrome." (PMID 35806237, 2022).
colorectal carcinoma (3 papers, 2018 to 2025). A malignant epithelial neoplasm that arises from the colon or rectum and invades through the muscularis mucosa into the submucosa. "DSE gene was initially identified as SART2 in colorectal carcinoma tissues, suggesting a potential immunogenic role of DS in cancer." (PMID 40867602, 2025). "In the past, DSE was considered a cancer cell antigen, and was called squamous cell carcinoma antigen recognized by T-cells 2 (SART2); it was supposedly highly expressed in most squamous cell carcinomas from various organs, including a subpopulation of colorectal carcinoma." (PMID 29864158, 2018).
glioma (3 papers, 2018 to 2024). A benign or malignant brain and spinal cord tumor that arises from glial cells (astrocytes, oligodendrocytes, ependymal cells). "The present study showed that DSE is frequently upregulated in human glioma tissue and cell lines, and DSE upregulation in glioma tissue is associated with a worse tumor grade and poor overall survival." (PMID 29864158, 2018). "In contrast, there was DSE protein expression in a great portion of the glioma tissue and cell lines, and elevated DSE expression is associated with poor survival." (PMID 29864158, 2018). "Here we demonstrated that CS56 staining is moderately associated with CHSY1 expression in human glioma tissue (rs = 0.676), suggesting that other CS modification enzymes, such as DSE and CHSTs, may also modulate CS56 epitopes." (PMID 32019907, 2020). "Previous studies have demonstrated that DSE is overexpressed in several cancers, such as glioma, breast cancer, and hepatocellular carcinoma, and regulates growth factor signalling in cancer cells." (PMID 38553479, 2024). "Our data revealed that DSE was highly expressed in 73% (56/77) of the glioma tumors, whereas all the normal brain tissues exhibited very weak DSE expression (two-sided Fisher exact test, P = 0.0024)." (PMID 29864158, 2018). "In the present study, we determined the expression of DSE in gliomas by consulting a public database and conducting immunohistochemistry on a tissue array." (PMID 29864158, 2018). "This evidence indicates that upregulation of DSE in gliomas contributes to malignant behavior in cancer cells." (PMID 29864158, 2018). "DSE knockdown suppresses malignant phenotypes, whereas DSE overexpression enhances glioma cell malignancy, both in vitro and in vivo." (PMID 29864158, 2018). "The immunohistochemical investigation revealed that DSE was expressed in the paranuclear and perinuclear cytoplasm of certain glioma tissue." (PMID 29864158, 2018). "For the first time, the present study has shown that dermatan sulfate epimerase (DSE) is capable of regulating glioma cell malignancy in vitro and in vivo, and the ErbB pathway is involved in this process." (PMID 29864158, 2018). "The present study demonstrates a pathophysiologic role of DSE in glioblastoma cells, and elucidates the biological functions of aberrant CS/DS expression in glioma progression." (PMID 29864158, 2018). "Our search of the ONCOMINE database showed that 6 out of 26 analyses (23%) of brain and CNS cancers revealed a greater than two-fold increase in the level of DSE, compared with normal tissue." (PMID 29864158, 2018). "Our results also indicated that DSE modulates DS chain formation in glioma cells." (PMID 29864158, 2018). "Our investigation revealed that DSE was upregulated in gliomas compared with normal brain tissue." (PMID 29864158, 2018). "The formation of DS on proteoglycans is regulated by DSE expression in glioma cells." (PMID 29864158, 2018). "We next determined whether DSE regulates the ErbB signaling pathways in glioma cells." (PMID 29864158, 2018). "Furthermore, a search of the REpository for Molecular BRAin Neoplasia DaTa (REMBRANDT) database revealed that high expression of DSE is associated with worse overall survival in glioma patients (n = 329), whereas DSEL expression does not correlate with patient outcomes." (PMID 29864158, 2018). "We conducted an immunohistochemical investigation of DSE protein expression in a glioma tissue array containing 77 primary glioma tissue samples and 5 non-tumor brain tissue samples." (PMID 29864158, 2018). "However, the role of DSE in gliomas has never been explored." (PMID 29864158, 2018).
melanoma (3 papers, 2016 to 2025). A malignant, usually aggressive tumor composed of atypical, neoplastic melanocytes. "DSE has been reported to act as a tumor suppressor in melanoma by regulating extracellular matrix interactions and immune cell infiltration." (PMID 40963856, 2025). "In order to reveal the function of DSE in melanoma, adenovirus transfection technique was used to construct melanoma cell lines with stable high expression or knockdown expression of DSE." (PMID 37833287, 2023). "The purpose of this study was to investigate the correlation between DSE expression and melanoma progression and the molecular mechanism that promotes melanoma progression." (PMID 37833287, 2023). "Together, these results suggest that DSE is downregulated in melanoma tissues, and that high expression of DSE can promote melanoma progression by inducing immune cell infiltration and VCAN expression." (PMID 37833287, 2023). "Our studies on collected melanoma tissues and cells also found that DSE protein was consistently underexpressed in melanoma tissues." (PMID 37833287, 2023). "Both data analysis and our animal models suggest that high expression of DSE in melanoma induces intratumoral infiltration of immune cells and promotes intratumoral levels of killer molecules." (PMID 37833287, 2023). "To further verify these results in vivo, we constructed a mouse subcutaneous tumor model using DSE overexpressed or knockdown melanoma cells." (PMID 37833287, 2023). "DSE silenced or overexpressed melanoma cells were constructed to detect the effect of DSE on melanoma cells, and it was found that the up-regulation of DSE significantly inhibited the proliferation, migration and invasion of melanoma cells." (PMID 37833287, 2023). "In order to further explore the molecular mechanism by which DSE inhibits melanoma progression, the transcriptome of control A875 and A875 cells with knockdown DSE was analyzed." (PMID 37833287, 2023). "The results showed that the mRNA and protein levels of DSE were significantly down-regulated in melanoma tissues." (PMID 37833287, 2023). "The TCGA database was used to analyze the influence of DSE expression level on the prognosis of melanoma patients, and Kaplan-Meier survival curve showed that patients with low DSE expression had poor prognosis (p < 0.01)." (PMID 37833287, 2023). "Together, these results suggest that DSE is significantly down-regulated in melanoma tissue and leads to poor prognosis in melanoma patients." (PMID 37833287, 2023). "Together, these in vitro results suggest that DSE inhibits proliferation, invasion, and migration of melanoma cells." (PMID 37833287, 2023). "In this study, we found that the level of DSE in melanoma tissues was significantly reduced, and the high expression of DSE inhibited the growth, invasion and migration of melanoma cells." (PMID 37833287, 2023). "Our study indicates that in NC-derived neuroblastoma and melanoma, DSE expression is correlated with gene sets for various migratory properties of cancer cells, including EMT, invasion and metastasis." (PMID 27101845, 2016). "Moreover, immunofluorescence staining further demonstrated that DSE was significantly underexpressed in melanoma tissues." (PMID 37833287, 2023). "Moreover, VCAN knockdown also significantly eliminated the inhibitory effect of DSE on melanoma invasion and migration." (PMID 37833287, 2023). "However, in this study, the proteomics of melanoma tissues combined with the RNA-seq analysis of the melanoma group of TCGA found that the mRNA and protein levels of DSE in melanoma tissues were significantly decreased compared with paracancer tissues." (PMID 37833287, 2023). "In addition, we constructed a tumor lung metastasis model by injecting melanoma cells into the tail vein of nude mice, and found that DSE overexpression significantly inhibited melanoma lung metastasis, while DSE knockdown promoted melanoma metastasis." (PMID 37833287, 2023).
melanoma (continued). "In addition, our results suggest that DSE regulates the progression of melanoma by regulating the expression of VCAN." (PMID 37833287, 2023). "In addition, we further examined the protein expression of DSE in a variety of melanoma cell lines, and found that DSE expression was decreased in most melanoma cell lines, while A875 cells maintained high DSE expression." (PMID 37833287, 2023). "Therefore, activation of the DSE-VCAN axis in melanoma tissue is expected to be a new way of melanoma treatment." (PMID 37833287, 2023). "In addition, low expression of DSE promotes melanoma cell growth, invasion and metastasis, and is closely associated with poor prognosis of melanoma patients." (PMID 37833287, 2023). "Therefore, DSE expression in melanoma may induce infiltration of CCl5-producing killer T cells and natural killer cells." (PMID 37833287, 2023). "In conclusion, our study shows that the DSE-VCAN axis is significantly inhibited in melanoma tissues, and activation of this pathway is expected to be a new way of melanoma treatment." (PMID 37833287, 2023). "Mechanistically, DSE promoted the expression of VCAN, which inhibited the biological activity of melanoma cells." (PMID 37833287, 2023). "Subsequently, we conducted a joint analysis of proteomic data and TCGA human melanoma RNA-seq data, and found that the mRNA and protein levels of 34 genes, including DSE, VEPH1, SFRP4, TTN, STSE, were consistently down-regulated in melanoma tissues." (PMID 37833287, 2023). "DSE overexpression significantly inhibited the proliferation of melanoma cells, while VCAN knockdown inhibited the effect of DSE overexpression." (PMID 37833287, 2023). "The effect of DSE on the viability of melanoma cells was detected by CCK-8 assay, and it was found that overexpression of DSE significantly inhibited the proliferation of A2508 cells." (PMID 37833287, 2023). "The correlation between DSE and VCAN expression in melanoma tissues was analyzed by immunofluorescence staining, and a significant positive correlation was found between DSE expression and VCAN expression." (PMID 37833287, 2023). "Tumor volume and weight measurements showed that DSE overexpression significantly inhibited melanoma growth, while VCAN knockdown reversed the inhibitory effect of DSE on melanoma." (PMID 37833287, 2023). "Human DSE expression correlates with genetic markers of EMT, invasion and metastasis in both neuroblastoma and melanoma, which suggests a potential role of DS-epi1 in NC-derived cancers." (PMID 27101845, 2016). "In addition, by injecting melanoma cells into the caudal vein of nude mice to construct a tumor lung metastasis model, we also found that VCAN knockdown eliminated DSE-inhibited melanoma lung metastasis." (PMID 37833287, 2023). "However, the expression and function of DSE in human melanoma have not been reported." (PMID 37833287, 2023).
breast carcinoma (2 papers, 2022 to 2024). "The present study provides additional evidence for the role of DSE in bringing about the death of hepatic, colorectal, and breast cancer cells by apoptosis." (PMID 36079792, 2022).
laryngeal carcinoma (2 papers, 2010 to 2011). Carcinoma that arises from the laryngeal epithelium. "Moreover, expression of DSE was found to be altered in laryngeal cancer specimens when compared to normal tissue samples." (PMID 21646684, 2011). "In our study, the most clear observations in laryngeal cancer were the significant decrease of CHSY3, CHST3 and D4ST1, and the significant increase of DSE." (PMID 20929582, 2010).
Musculocontractural EDS (2 papers, 2023). "Musculocontractural EDS (mcEDS) is a rare subtype of EDS caused by mutations in the genes encoding carbohydrate sulfotransferase 14 (mcEDS-CHST14; MIM#601776) or dermatan sulfate epimerase (mcEDS-DSE; MIM#615539)." (PMID 36833362, 2023).
ovarian carcinoma (2 papers, 2011 to 2020). A malignant neoplasm originating from the surface ovarian epithelium. "Among the metabolic pathway-related genes, ME1 and DSE have been reported to be associated with ovarian cancer." (PMID 33177242, 2020). "A metabolic pathway was the most significant pathway enriched by GGPS1, ME1, DSE, NTPCR, PPOX, and PC.ME1 and DSE have been reported to be associated with the development of ovarian cancer in previous studies." (PMID 33177242, 2020). "Significantly, abnormal dermatane sulphate composition has also been reported in both ovarian carcinomas and ovarian cancer cell lines, providing further support for a putative role of DSE in our ovarian model." (PMID 21646684, 2011).
squamous cell carcinoma (2 papers, 2018 to 2023). A carcinoma arising from squamous epithelial cells. "Previous reports have shown that DSE is often upregulated during carcinogenesis in certain types of cancer, such as glioma and squamous cell carcinoma, and can regulate growth factor signaling in cancer cells." (PMID 37833287, 2023). "Initially, DSE was highly expressed in squamous cell carcinoma of different origins, and therefore was considered as a cancer cell antigen, named squamous cell carcinoma antigen recognized by T-cells 2 (SART2)." (PMID 37833287, 2023).
astrocytoma (1 paper, 2018). "In addition, DSE expression in glioblastoma is significantly higher than that in astrocytoma, oligodendroglioma, and normal brain tissue." (PMID 29864158, 2018).
bipolar disorder (1 paper, 2023). A disorder of the brain that causes unusual shifts in mood, energy, activity levels and the ability to carry out day-to-day tasks. "It should be noted that DSE is identical to SART2 (squamous cell carcinoma antigen recognized by T cells 2), which encodes a protein with unknown function highly expressed in cancer cells and tissues, and that DSEL is identical to C18orf4, which is a candidate gene for a bipolar disorder." (PMID 36833436, 2023).
brain tumors (1 paper, 2018). "Compared with normal brain tissue, 6 out of 26 independent datasets indicated that only DSE is significantly upregulated in brain tumors, especially in grade IV glioblastomas." (PMID 29864158, 2018).